MMP9 (matrix metallopeptidase 9)
Diseases named in the same sentence as MMP9 in open-access papers (continued):
Sharing a sentence is not in itself a finding about the gene and the disease.
melanoma (continued). "Moreover, MMP9 was shown to be secreted by keratinocytes under the influence of melanoma in the reconstructed skin model, which is consistent with our findings." (PMID 36123693, 2022). "In addition, the MMP-9 expression level was inhibited by DPG in melanoma cells stimulated by TPA and compared to only TPA-treated cells." (PMID 35992881, 2022). "β-Carotene treatment downregulates the expression of MMP-2 and MMP-9 by suppressing the nuclear translocation of p65, p50, c-Rel subunits of nuclear factor-kappa B, and other transcription factors, such as c-fos, a component of AP-1, in B16F-10 melanoma cells." (PMID 33809289, 2021). "Therefore, we infer that MMP9 plays an important part in the transformation of normal melanocytes into melanoma." (PMID 33854593, 2021). "Therefore, TRAF6 can enhance melanoma invasion and metastasis through the regulation of MMP9 production." (PMID 33430277, 2021). "Inhibition of IL‐33 and MMP‐9 restore the TIL‐mediated killing effects in melanoma cells." (PMID 34486239, 2021). "In addition, although Mmp-2 and Mmp-9 are known to play important roles in the migration and invasion processes of melanoma, Mmp-14 can activate both." (PMID 34207144, 2021). "These factors then induce the secretion and activation of MMP9 in VGP melanoma." (PMID 33430277, 2021). "Next, we investigated the impact of MMP‐9 inhibition on melanoma cell killing by TILs in vivo." (PMID 34486239, 2021). "CAFs can increase MMP9 expression and enhance growth and metastasis of melanoma." (PMID 34977016, 2021). "Therefore, it is anticipated that the discovery of novel anticancer compounds that inhibit the expressions of MMP-2, and MMP-9 by VEGF will contribute toward overcoming skin cancer via the regulation of melanoma growth and metastasis." (PMID 35011253, 2021). "Hypermethylation at the CpG-2 intragenic region is observed with higher MMP9 expression levels, and the MMP9 intragenic methylation hotspot may be responsible for the MMP9 overexpression in melanoma cell lines." (PMID 34943943, 2021). "Considering the role of Let‐7i in regulating target genes involved in melanoma carcinogenesis, MMP9, c‐Myc and PTEN, which have a potential role in controlling the biology of melanoma, were selected from the mirdb.org website (MicroRNA target prediction database) or previous studies." (PMID 34096173, 2021). "Furthermore, it has been demonstrated that stromal fibroblast-derived MMP-9, involved in the cleavage of PD-L1 from melanoma cell surface, leads to anti-PD-1 therapy resistance in melanoma." (PMID 34067929, 2021). "Furthermore, MMP-9 is frequently involved in the development of melanoma and promotes inflammation, angiogenesis, and invasion of tumor keratinocytes." (PMID 34744703, 2021). "Similarly, MMP‐9 also eliminates MICA/B expression in melanoma cells, evading T‐cell recognition for killing." (PMID 34486239, 2021). "Interestingly, previous studies on melanoma have reported gene body DNA hypermethylation and increased mRNA expression of MMP9, suggesting possible cell-type specificity of DNA methylation pattern." (PMID 34034702, 2021). "Here, we demonstrate that DLC1, which is known to function as a tumor suppressor in various cancer types, plays oncogenic roles in melanoma, through the association of transcription factor FOXK1 in the nucleus for cooperative activation of MMP9 expression to promote invasion and metastasis." (PMID 32214200, 2020). "Finally, OPN is able to induce the activation of MAP3K1 signaling pathways regulated by MMP-9 resulting in the proliferation of melanoma cells and pulmonary metastases." (PMID 32392801, 2020). "TRAF6 promotes the invasion and metastasis of melanoma, glioblastoma, gastric cancer and other tumors by overexpressing MMP-9, leading to malignant transformation of tumors and down-regulation of TRAF6 in A549 lung adenocarcinoma cells effectively reduces MMP9 expression." (PMID 32905356, 2020).
melanoma (continued). "To further substantiate the cooperative action of the DLC1–FOXK1 complex in regulating MMP9 expression and promoting melanoma invasiveness, we examined the ability of DLC1 OE, FOXK1 OE, and both to restore MMP9 expression and melanoma invasion in DLC1 KD cells." (PMID 32214200, 2020). "We also investigated the correlation of the seven prognostic-associated TBCs between MMP-related genes (MMP2, MMP9, MMP7, MMP14, BSG, EGFR, MMP1, MMP3) and EMT-associated genes (TWIST1, VIM, CDH2, ACTA2, ZEB1), which also indicated a central role of TBCs in melanoma." (PMID 33194704, 2020). "Clear expression of MMP-9 by the melanoma cells was observed at the melanoma/dermal border in the Mel-RhS, consistent with early invasive events and suggesting that the melanoma cells were actively degrading the BM through MMP-9 release." (PMID 32507967, 2020). "In the early-AJCC-staged melanoma group, we exclusively detected in the enriched endothelial fraction E-CMC, MCAM expression, 5′-portion, and both isoforms, associated with VE-CADH, MMP2, and MMP9 (these last genes mostly expressed)." (PMID 32548126, 2020). "We thus wondered whether active MMP-9, exclusively observed when Tspan8+ melanoma cells were surrounded by keratinocytes, coincided with low levels of TIMP-1." (PMID 32455575, 2020). "In particular, it was proved that the high levels of MMP-9 in melanoma patients might be due to the dysregulation of the TGFβ pathways where the alterations in the levels of NF-κB is able to induce the overexpression of MMP-9 via OPN activation." (PMID 32392801, 2020). "Additionally, SK-MEL-28 and A375 melanoma cell lines with MMP9 KD also significantly decreased the PD-L1 mRNA and protein levels." (PMID 32988398, 2020). "In addition, to validate the regulation of PD-L1 expression through MMP2/9, we generated the stable overexpression (OE) MMP2 or MMP9 melanoma cell lines." (PMID 32988398, 2020). "Furthermore, our results indicated that curcumol decreased the expression of MMP2 and MMP9 in mouse melanoma B16 cells." (PMID 32194780, 2020). "Indeed, our recent evidence showed that the OPN and MMP-9 are strongly involved in several neoplastic processes in melanoma, including ECM degradation, invasion of the surrounding tissues, metastasis formation and loss of apoptosis." (PMID 32392801, 2020). "Nevertheless, it is still unclear whether and how MMP-9 produced by melanoma cells, nearby host cells, or both, might be involved in late-stage melanoma." (PMID 32455575, 2020). "In mice, forced MMP-9 expression in melanoma cells enhanced lung colonization which was reduced in MMP-9-deficient mice, indicating that MMP-9 produced by neoplastic and host cells might be equally important for the initiation of metastatic spreading." (PMID 32455575, 2020). "We observed that non-invasive melanoma cells gained strong invasive properties after the ectopic expression of Tspan8 in matrigel and SR concomitantly to the production of high levels of active MMP-9." (PMID 32455575, 2020). "Among the commonly downregulated targets involved in cancer invasion and metastasis, we selected secreted MMP9 for further studies based on previous reports that it is required for both NC cell migration and melanoma invasiveness via the degradation of extracellular matrix." (PMID 32214200, 2020). "Moreover, injections of SM were found to significantly decreased number of surface lung metastasis of B16 melanoma-bearing mice and lead to up-regulation of E-cadherin and down-regulation of MMP-9 in metastatic foci." (PMID 33327637, 2020). "This coincided with secretion of matrix metalloproteinase 9 (MMP-9) by melanoma cells." (PMID 32507967, 2020). "In our study, TRIM59-/ -macrophages mediated upregulation of the PI3K and ERK signaling pathways in B16 melanoma cells, promoting MMP-9 and Madcam1 expression and stimulating migration and invasion in vitro, as well as tumorigenesis, EMT, and metastasis in an in vivo tumor model." (PMID 31600735, 2019).
melanoma (continued). "CD133 may therefore play an essential role in invasion and metastasis via upregulation of MMP2/MMP9, leading to tumor progression, and represents an attractive target for intervention in melanoma." (PMID 31623313, 2019). "Matrix metalloproteinase-9 (MMP-9) could be one of them as its role as indicator of invasiveness in melanoma have been explored." (PMID 30154717, 2018). "Overall, the mechanisms of the antimetastasis effect of GBEE on B16-F10 melanoma metastasis involve regulating PI3K/Akt/NF-κB/MMP-9 signaling pathway and further inhibiting tumor cell proliferation, migration, heterogeneous adhesion, and ECM and BM degradation." (PMID 30046339, 2018). "In addition, the percentage of MMP-9 serum variations at different times during the treatment with BRAF inhibitors were analyzed in melanoma patients." (PMID 30154717, 2018). "Among these, MMP-9 may be a right marker candidate easily detected in the peripheral blood samples from melanoma patients." (PMID 30154717, 2018). "These encouraging data support the notion that MMP-9 may be considered a marker of response to dabrafenib in melanoma cells." (PMID 30154717, 2018). "In this study, MMP-9 was evaluated in melanoma cells after treatment with dabrafenib." (PMID 30154717, 2018). "The SLNCR1/AR/Brn3a ternary complex has a high affinity for the AR and Brn3a binding sites located upstream of the MMP9 transcription start site, and the cooperative binding of AR and Brn3a to its promoter increases MMP9 expression and activity and, thus, increases the invasion of melanoma cells." (PMID 29416704, 2018). "Therefore, in the present study, the modulation of MMP-9 in melanoma after treatment with B-RAF inhibitors was analyzed through different experimental approaches." (PMID 30154717, 2018). "Moreover, MMP-9 was demonstrated to be a marker of aggressiveness in several tumors, including melanoma; while, its role as an indicator of therapeutic response was not fully investigated yet." (PMID 30154717, 2018). "It has previously been shown that activated T cell exosomes could upregulate MMP9 expression in murine melanoma cells and hepatocellular carcinoma-derived exosomes could increase MMP9 secretion in hepatocytes." (PMID 30008265, 2018). "In addition to the observed effects on mRNA expression of CSPG4 and pro-MMP2, the expression of another gelatinase, MMP9, was also increased in the malignant melanoma cells and following silencing of ARSB." (PMID 27926479, 2017). "In melanoma, MMP-2 and MMP-9 overexpression has been associated with EMT, invasion, and metastasis." (PMID 26517521, 2016). "Furthermore, TRAF6 can directly interact with and ubiquitinate BSG leading to MMP9 induction, which serves as a mechanism for melanoma invasion and metastasis." (PMID 26769849, 2016). "Afterwards, we proceeded to stratify melanoma samples into low (below 30th percentile), medium (between 30th and 70th percentile) and high (above 70th percentile) groups according to the levels of MMP-9 mRNA expression." (PMID 27115178, 2016). "Therefore, in the present study we performed in silico and in vitro analyses to assess the methylation patterns of MMP9 gene in melanoma and its implication in MMP-9 mRNA overexpression." (PMID 27115178, 2016). "Therefore, in addition to DPI, we determined the effect of honokiol and NAC on the levels of MMP-2 and MMP-9 in melanoma cells." (PMID 26760964, 2016). "Given the well-documented role of MMP9 in cancer metastasis and the direct effect of BSG ubiquitination on cell invasiveness in our present study, TRAF6-mediated BSG ubiquitination represents a novel mechanism underlying BSG-dependent melanoma metastasis." (PMID 26769849, 2016). "Recently, it was shown that MMP9 drives tumor progression and metastasis of triple negative breast cancer and increased expression of MMP9 has been found in the early steps of melanoma." (PMID 25699257, 2015).
melanoma (continued). "The melanoma cell lines showed different growth patterns in the brain, and these differences were associated with differences in expression of the angiogenic factors VEGF-A and IL-8 and the matrix metalloproteinases MMP-2 and MMP-9." (PMID 26667022, 2015). "MMP9 is activated early during melanoma progression and is secreted by keratinocytes." (PMID 24466237, 2014). "In addition, gene expression of IL-6, MDR-1, and MMP-9 in the picked-up B16F1 spheroids was used to evaluate the effect of spatial relationship to endothelial cells (HUVEC) on the invasive capacity of melanoma cells." (PMID 25058006, 2014). "In addition acidic pHe induces MMP-9 expression in mouse melanoma cells through NF-κB activation with change to a fibroblastic morphology." (PMID 25493076, 2014). "Additionally, CREB is known to play essential roles in regulating MMP2 and MMP9 expression in melanoma and pancreatic cancer cells." (PMID 24113161, 2013). "The present study stimulated melanoma B16 cells with α-MSH and demonstrated the increased expression of melanin production to be accompanied with the upregulation of CSC-associated molecules (Wnt-1/β-catenin, c-Kit, MITF, and MMP-9) and invasion ability." (PMID 23762150, 2013). "Interestingly, in a mouse melanoma cell line extracellular acidic pH was reported to induce MMP9 expression through phospholipase D-triggered MAPK activation." (PMID 24098477, 2013). "Actually, several reports revealed that the expression of MMP-9 on tumors was correlated with the progression or prognosis of several skin tumors such as malignant melanoma, squamous cell carcinoma, basal cell carcinoma, mycosis fungoides, extramammary Paget's disease, and angiosarcoma." (PMID 23606867, 2013). "This clearly suggests that expression of MMP-9 is an early event in melanoma progression." (PMID 20631829, 2010). "We hypothesized that the MMP-9 polymorphisms might alter the expression and activity of the enzyme, increasing ECM degradation and invasion, leading to melanoma progression." (PMID 17346338, 2007). "To date, and to the best of our knowledge, there are no reports on associations between polymorphisms in MMP-9 and melanoma." (PMID 17346338, 2007). "Furthermore, αV/β5 integrin is also involved in the highly aggressive phenotype of melanoma cells such as cilengitide, an arginine–glycine–aspartic acid (RGD) broad-spectrum integrin inhibitor peptide, as well as reduced ECM invasion and the secretion of and MMP-9 by melanoma cells." (PMID 39859367, 2025). "However, serum MMP-9 levels were notably elevated in melanoma patients compared to controls." (PMID 39766118, 2024). "Indeed, peritumoral injection of CRAMP (the mouse ortologe of LL-37) increased the mRNA expression of CXCL5, IL23A, MMP1, and MMP9 in B16F10 melanoma in vivo, suggesting that LL-37 could enhance pro-angiogenesis in melanoma." (PMID 36980564, 2023). "Similarly, during melanoma progression, MMP-9 is also activated very early." (PMID 36674806, 2023). "Moreover, PPARβ/δ inhibition promoted the gene and protein expression of matrix metalloproteinase 9 (MMP-9) and increased the adhesion of mouse melanoma B16F10 to endothelial cells leading to enhanced motility and invasiveness, which are crucial for melanoma metastasis." (PMID 36834531, 2023). "Therefore, targeting LL-37, MMP-9, and TAMs could be a potential anti-angiogenic drug target to suppress the local invasion of melanoma cells, which might improve the OS of melanoma patients in the future." (PMID 36980564, 2023). "MiR-204-5p by targeting MMP9 and Bcl-2 could inhibit melanoma growth and resistance to 5-FU." (PMID 33954114, 2021). "Importantly, high levels of MMP9 and BRAF V600E MTs are associated with poor progression-free survival in melanoma patients, and activation of NRF2 through this pathway might be critical for tumor cell proliferation." (PMID 34069882, 2021).
melanoma (continued). "Interestingly, an in vitro study reported that the binding of laminin-5 to melanoma cells enhances the production of MMP-9 (type IV collagenase), which is thought to be fundamental for invasive cells to degrade the basement membrane, invade, and thus modify the surrounding tumor stroma." (PMID 34067929, 2021). "Moreover, our finding is also in line with the observation that the production of MMP-9 by melanoma cells may be regulated by antioxidants added externally." (PMID 32486135, 2020). "Therefore, MMP-9 may be considered a promising molecule for the management of melanoma patients due to its role as a biomarker and therapeutic target." (PMID 32392801, 2020). "Moreover, it has also been demonstrated that epigenetic modifications may lead to the up-regulation of MMP-9 in melanoma and other cancer types, as explained in the following paragraphs." (PMID 32392801, 2020). "Thus, we determined the expression of known NF-κB targets in melanoma, e.g., MMP9, CCL20 and IL1B." (PMID 32712598, 2020). "Furthermore, to test whether SB-3CT have any activity in the context of KD of MMP2 or MMP9, we treated melanoma cell lines (SK-MEL-28 and A375) transfected with shMMP2, shMMP9, or shNC with SB-3CT." (PMID 32988398, 2020). "In melanoma, loss of let-7a, which is a negative regulator of ITGB3, leads to elevated levels of integrin α3, while suppression of let-7b indirectly enhances the production of matrix metalloproteinase (MMP)-9, facilitating collagen degradation and cell invasion." (PMID 33203119, 2020). "Also, neutralization of MMP9 increased the oncolytic efficiency of tanapox virus for melanoma." (PMID 32595353, 2020). "Moreover, resveratrol was proven to be effective in inhibiting α-MSH-induced cancer stem cell-associated molecules, such as Wnt-1/β-catenin, c-Kit, MITF, and matrix metalloproteinase 9 (MMP-9), decreasing the cell viability, as well as suppressing the invasion of melanoma B16 cells." (PMID 30813264, 2019). "In vitro data were validated in 26 melanoma patients, of which 14 treated with BRAF inhibitor alone and 12 treated with both BRAF and MEK inhibitors, by ELISA assay and droplet digital PCR for measuring MMP-9 serum levels and circulating-free DNA BRAFV600E mutation, respectively." (PMID 30154717, 2018). "In addition, the combination of J-4 and Celecoxib could induce MET and decrease the expression of MMP-2/MMP-9 in melanoma cells, which in turn inhibit the migration and invasion of melanoma cells." (PMID 28865485, 2017). "This correlation may give further insights on the role of MMP-9 upregulation in melanoma." (PMID 27115178, 2016). "Notably, Rangaswami described that MMP-9 is activated in melanoma." (PMID 27115178, 2016). "We report that the melanoma cell lines showed highly different patterns of vascularization and invasion in the brain and, furthermore, these differences were associated with differences in expression of the angiogenic factors VEGF-A and IL-8 and the matrix metalloproteinases MMP-2 and MMP-9." (PMID 26667022, 2015). "The human melanoma cell lines A-07, D-12, R-18, and U-25 showed characteristic patterns of vascularization and invasion in the brain, and these differences were associated with differences in expression of the angiogenic factors VEGF-A and IL-8 and the matrix metalloproteinases MMP-2 and MMP-9." (PMID 26667022, 2015). "However, the concentrations of MMP-9 were significantly higher in those with melanoma." (PMID 26002577, 2015). "Moreover, acidity-induced experimental pulmonary metastasis was inhibited by treatment with the general MMP inhibitor GM6001 and the general cysteine proteinase inhibitor E-64, suggesting that MMP-2 and MMP-9 are required for the development of pulmonary metastases in our melanoma models." (PMID 26667022, 2015).